ANXA2 (annexin A2)
Diseases named in the same sentence as ANXA2 in open-access papers (continued):
Sharing a sentence is not in itself a finding about the gene and the disease.
cancer (continued). "This suggests an important role of p16 in the increase in the ANXA2 expression level in cancer cells." (PMID 21799732, 2011). "Although ANXA2 (annexin A2) is a substrate for a variety of protein kinases, and plays an important role in plasmin regulation and in cancer cell invasiveness and metastasis, ANXA2P3 (annexin A2 pseudogene 3) is a novel marker not being previously reported." (PMID 17411443, 2007). "Annexin A2 overexpression is common in various carcinomas, and annexin A2 can interact with c-Myc in increasing cell proliferation." (PMID 16507464, 2006). "Furthermore, Listeria-based ANXA2-targeted cancer immunotherapy sensitizes pancreatic ductal adenocarcinoma (PDAC) to treatment with the immune checkpoint inhibitor anti-PD-1 antibody, reshaping the immune microenvironment." (PMID 40234383, 2025). "However, our previous investigations revealed that ANXA2 plays a crucial role in resisting cancer cell death, and studies have shown that high ANXA2 expression in cancer cells is often associated with resistance to radiotoxicity and chemotoxicity." (PMID 40234383, 2025). "Therefore, we aimed to further explore the role of the antiapoptotic mechanisms of ANXA2 in cancer cell resistance to radiotherapy and chemotherapy." (PMID 40234383, 2025). "We hypothesize that whether ANXA2-induced autophagy in cancer cells is beneficial for resisting apoptosis depends on the extent of autophagy." (PMID 40234383, 2025). "Next, we asked whether the plasmin production mediated by annexin A2/S100A11 complex on the cell surface of the LOXL4-positive TNBC cells promotes cancer metastasis." (PMID 38595825, 2024). "Annexin A2 is a protein that plays a role in many important cell functions, but when its levels are not properly regulated, it can contribute to the development of cancer, particularly in the digestive system." (PMID 39594718, 2024). "Therefore, decreased HAR1A in NSCLC potentiates cancer growth and metastasis by upregulating the ANXA2." (PMID 38688909, 2024). "Furthermore, ECA109 stable ANXA2-knockdown cancer cells were subcutaneously injected into the right flank of nude mice." (PMID 38658569, 2024). "Therefore, decreased HAR1A in NSCLC potentiates cancer growth and metastasis by upregulating the ANXA2/NF-κB axis." (PMID 38688909, 2024). "Thamake and coworkers synthesized homobifunctional spacer, bis(sulfosuccinimidyl) suberate (BS3) tailoring curcumin PLGA nanoparticles and reported an enhancement linkage of Annexin A2 leading to proficient specific delivery to Annexin-A2-positive MDA-MB-231 cancer cells." (PMID 36904364, 2023). "We explored the correlation between ANXA2 expression and immune infiltration in 33 types of cancer." (PMID 36713082, 2023). "Therefore, ANXA2 is a potential immune-related marker and a promising immunotherapy target in pan-cancer." (PMID 36713082, 2023). "Furthermore, ANXA2 promotes cancer cell invasion into the squamous epithelium basement membrane and underlying connective tissue by interacting with intracellular proteins that are essential for metastasis." (PMID 37185759, 2023). "Further research on ANXA2 may lead to new breakthroughs for cancer diagnosis and immunotherapy, and further improve the prognosis of cancer patients." (PMID 36713082, 2023). "Differential expression of ANXA2 might contribute to the occurrence and development of various cancers." (PMID 36713082, 2023). "Our study provides a theoretical support for the application of ANXA2 in cancer immunotherapy." (PMID 36713082, 2023). "This suggests Annexin A2 has an integral role in the degradation of fibronectin by cancer cells and modulating Annexin A2 activity could be a viable therapeutic strategy, in the yet unsuccessful targeting of plasmin-mediated cancer cell dissemination." (PMID 37941562, 2023). "Relationship between ANXA2 expression and DNA methylation in pan-cancer." (PMID 36713082, 2023).
cancer (continued). "In cancer, ANXA2 usually plays a pro-inflammatory role, and the excessive angiogenesis maintained by ANXA2 under inflammatory conditions may induce tissue damage and lead to poor prognosis." (PMID 36713082, 2023). "We speculate that he EMT process may be the link between ANXA2 and CD276, and CD276 may be the key factor for breakthrough in cancer immunotherapy targeting ANXA2, which needs more research to prove." (PMID 36713082, 2023). "Our results indicated that ANXA2 may be a promising immune-related prognostic biomarker in a variety of cancers." (PMID 36713082, 2023). "In addition, further clarification of the relationship between ANXA2 and patient prognosis requires rigorous experimental validation and more multicenter prospective studies, guiding ANXA2 application in the treatment of cancer patients." (PMID 36713082, 2023). "Our previous findings showing the association of Annexin A2 expression with metastatic progression, combined with our new observations of how Annexin A2’s role is heavily influenced by the ECM points to the interaction between Annexin A2 and collagen-I as a target of interest in cancer progression." (PMID 37941562, 2023). "Thus far, peptides have been discovered for developing cancer‐specific imaging probes via targeting ANXA2." (PMID 36453020, 2023). "We speculated that ANXA2 is more likely to exert significant physiological or pathological functions in normal tissues and cancers with high levels of ANXA2 protein expression." (PMID 36713082, 2023). "It is also necessary to discuss the unusual role of annexin A2 in cancer progression." (PMID 37091157, 2023). "We also found that the ANXA2 expression positively correlated with the StromalScore of 12 types of cancer (all r > .3, all p < .05), the ImmuneScore of 11 types of cancer (all r > .3, all p < .05) and the ESTIMATEScore of 11 types of cancer (all r > .3, all p < .05)." (PMID 36713082, 2023). "ANXA2 has been used as a valuable biomarker for both cancer diagnosis and prognosis." (PMID 36453020, 2023). "The use of Anxa2 antibodies has also been reported in other cancer treatments." (PMID 37955107, 2023). "The ANXA2 expression was high in 12 types of cancer and low in four types of cancer." (PMID 36713082, 2023). "In addition, ANXA2 plays a crucial role in membrane repair of many cell types, including cancer cells." (PMID 38092984, 2023). "We investigated the correlation between the ANXA2 expression and DNA methylation in pan-cancer." (PMID 36713082, 2023). "Consequently, we wanted to investigate the potential relationship between ECM dysregulation and Annexin A2 expression as both represent hallmarks of aggressive cancer progression." (PMID 37941562, 2023). "To test this hypothesis, we first tried to determine the effects of annexin A2 and integrin β-1 on cancer cell behaviors in vitro." (PMID 37091157, 2023). "This difference may be attributable to differences in the nuclear-to-cytoplasmic relocalization of PCNA, as reported in neutrophils, or the variable expression of Annexin A2, a membrane that traffics protein to lipid rafts, as reported in other cancers." (PMID 37686697, 2023). "The downregulation of Annexin A2 has been reported in several cancers (esophageal squamous cell carcinoma, oral squamous cell carcinoma, and prostate cancer), and might have an effect on PCNA migration to the membrane." (PMID 37686697, 2023). "Ultimately, Cua and colleagues suggested that annexin A2 might be taken into consideration as a qualified cancer immunotherapy target antigen and that 2448 could be further applied for therapeutic advantage." (PMID 38146364, 2023). "We explored the correlation between ANXA2 expression and 47 immune checkpoints in pan-cancer." (PMID 36713082, 2023). "Furthermore, a number of studies have linked phosphorylation of Annexin A2 to the promotion of EMT and metastatic cell behaviors in a variety cancer types." (PMID 37941562, 2023).
cancer (continued). "It is indicated that S100A10 may promote the invasiveness and metastasis of these cancer cells through an ANXA2-independent pathway." (PMID 36612197, 2022). "Increasing evidence indicates that AnxA2 is upregulated in several types of human cancer." (PMID 36428758, 2022). "ANXA2 was reportedly playing crucial roles in cancer growth and progression." (PMID 35163852, 2022). "ANXA2 is a multifunctional protein and known to act as a co‐receptor for tissue plasminogen activator (tPA) on the surface of endothelial and cancer cells, thereby affecting fibrinolytic activity and neoangiogenesis as well as invasive and metastatic properties." (PMID 34240826, 2022). "ANXA2 remains concentrated beneath the rupture point for an extended time, where it could act to reshape the cortical actin cytoskeleton, as proposed in cancer cells." (PMID 35207075, 2022). "It is worth highlighting that ANXA1 and ANXA2 have been linked to radio-chemoresistance and immunosuppression in HNC and other cancers, which poses a plausible application as adjuvant treatments to jointly improve treatment response and antitumor immune response." (PMID 36247003, 2022). "However, the expression of ANXA2 can be regulated through various substances, including those that are involved with inflammation and cancers." (PMID 36293376, 2022). "Finally, an original function in cancer was described for the extra-cellular S100A10 isoform in plasmin biogenesis through its tetramerization with ANXA2." (PMID 36232334, 2022). "The same group also explored expression patterns of Annexin A1 and Annexin A2, two structurally and phylogenetically related proteins, in tissue specimens from respiratory (nasal and laryngeal) and digestive (oral and pharyngeal) mucosa of non-cancer patients." (PMID 35563776, 2022). "Aberrant ANXA2 expression is detected in multiple cancers, and ANXA2 expression is reported to correlate with cancer proliferation, invasion and metastasis, which may be used as biomarker for cancer staging and prognosis prediction." (PMID 35371986, 2022). "This is because ANXA2 has been reported to function as a co‐receptor for tissue plasminogen activator (tPA) at the cell surface of endothelial and cancer cells, and the current study suggests the co‐localization, dependence and interaction between ANXA2 and EpCAM at the cell surface." (PMID 34240826, 2022). "It has been demonstrated that RACK1 could regulate ANXA2 phosphorylation to make it involved in the invasion and metastasis of drug-resistant carcinoma cells." (PMID 39290334, 2022). "It suggested that Rg5 and Rk1 might be promising natural compounds for cancer treatment by targeting Annexin A2." (PMID 34421584, 2021). "Similary, a DNA aptamer that binds AnxA2 on cancer cells could become a tool to diagnose and treat multiple myeloma." (PMID 33810523, 2021). "Overexpression of Anxa2 in cancer cells has widely been reported to impact human carcinogenesis." (PMID 33817317, 2021). "It suggests that ANXA2 may represent a latent target of diagnosis and an emerging biomarker of prognosis in cancer therapy." (PMID 33995636, 2021). "Aberrant expression of ANXA2 is observed in extensive range of cancer cells." (PMID 33995636, 2021). "It is known that ANXA2 expression is upregulated in board spectrum of cancer cells." (PMID 33995636, 2021). "In addition, ANXA2 and its receptor are critically involved in the adhesion and communication of cancer cells with osteoblasts." (PMID 34831167, 2021). "Anxa2 has been proven facilitating cancer progression via multiple aspects by interacting with other biomolecules, among which the Anxa2 rearrangement gene expression in cancer cells through oncogenic transcription factor like NF-κB, YAP1 in Hippo pathway and STAT3/6." (PMID 34502195, 2021).
cancer (continued). "Finally, other studies demonstrated the higher expression of serum exosomal-annexin A2 (exo-AnxA2) in BC patients compared to non-cancer females, especially for triple-negative BC (TNBC) rather than luminal and HER2-positive BC." (PMID 33803776, 2021). "ANXA2 is an important member of the annexin family of proteins expressed on the surface of endothelial cells, macrophages, mononuclear cells and various types of cancer cells." (PMID 34675316, 2021). "Moreover, ANXA2 is one of the most highly expressed proteins in exosomes derived from cancer cells, and exosomal ANXA2 triggers the activation of the STAT3, p38, and NF-κB pathways in and the enhanced secretion of TNFα and IL6 from macrophages." (PMID 34599143, 2021). "In addition, abnormal expression of ANXA2 is link to multidrug resistance in cancer treatment 41, 66, 93, 119-121." (PMID 33995636, 2021). "More attention has been focused on exploring therapies targeting ANXA2 in cancer treatment." (PMID 33995636, 2021). "Additionally, ANXA2 expressed more strongly in the cell membrane than that in the cytoplasm of carcinoma cells." (PMID 33995636, 2021). "At the cell surface, AnxA2 heterotetramer complex provides binding site for both plasminogen and tissue type plasminogen activator (tPA) and converts plasminogen into plasmin, which plays an important role in invasion and metastasis of cancer." (PMID 33374917, 2020). "It is well established that some annexins, including ANXA1 and ANXA2, can be secreted out of the cell through unconventional secretory mechanisms, with implications in many functions such as the endocrine regulation, inflammatory response and cancer." (PMID 31940782, 2020). "For instance, cancers expressing ANXA8 might be targeted with a strategy developed for targeting ANXA2." (PMID 32823855, 2020). "Notably, HIST1H1D, PSMD2, ANXA2 and SPTAN1 overexpression was associated with elevated protein content in cancer tissues, whereas KRT5 has been rarely observed at the protein level in these tissues." (PMID 32252346, 2020). "For ANXA2 there is a reduction in the positive staining between normal prostate and carcinoma." (PMID 32197509, 2020). "A high level of Anxa2 in cancer tissues is correlated to a highly aggressive phenotype." (PMID 31113450, 2019). "In summary, we observed increased expression of PRDX2 upon depletion of ANXA2 in cancer cells." (PMID 30959964, 2019). "Moreover, clinical studies have shown that Anxa2 overexpression is positively correlated to poor response to anticancer agents and rapid recurrence in cancer patients who had received chemotherapy." (PMID 31113450, 2019). "The expression of ANXA2 has been found in various malignant tumors." (PMID 31210752, 2019). "We then tested whether targeting ANXA2 with a Listeria-based therapeutic cancer immunotherapy would improve survival in a preclinical model of metastatic PDAC." (PMID 31113479, 2019). "Therefore, the observation in this current study supported a role of Lm-ANXA2 and the combination of Lm-ANXA2 and anti-PD-1 antibody in cancer treatment." (PMID 31113479, 2019). "Considering ANXA2 has been generally accepted as oncogene overexpressed in a vast of cancers correlated with tumorigenesis, which might be the target molecule of miR155HG sponging miRNA via bioinformatics analysis." (PMID 30898167, 2019). "Increased Anxa2 expression has been shown to be specific in many drug-resistant cancer cells." (PMID 31113450, 2019). "Moreover, recent studies have shown that Anxa2 is a key protein that links drug resistance and cancer metastasis." (PMID 31113450, 2019). "A high level of Anxa2 in cancer tissues is correlated with a highly aggressive phenotype." (PMID 31113450, 2019). "In summary, the interaction of HE4 and ANXA2 commonly exists in various cancer cells." (PMID 31210752, 2019). "Therefore, uncovering the detailed mechanisms through which Anxa2 promotes cancer progression is urgently required." (PMID 31113450, 2019).
cancer (continued). "Besides binding to hESCs, ch2448 was found to bind to various cancer cells and the antigen target was identified as Annexin A2." (PMID 31388993, 2019). "HE4 and ANXA2 can promote the proliferation, adhesion, invasion, and migration of cancer cells." (PMID 31210752, 2019). "Notably, two forms of annexin with antagonistic effects during cancer progression were identified: annexin A1, which inhibits antiapoptotic signaling pathways, and annexin A2, which promotes cancer cell proliferation." (PMID 31382537, 2019). "Increased Anxa2 expression appears to be specific in many drug-resistant cancer cells." (PMID 31113450, 2019). "Elevated Anxa2 expression seems a common event when cancer cells acquire drug resistance." (PMID 31113450, 2019). "The interaction of HE4 and ANXA2 exists in various types of cancer cells." (PMID 31210752, 2019). "Thus, ANXA2-expressing, Listeria-based immunotherapy targets a biologically important molecule for cancer development." (PMID 31113479, 2019). "ANXA2 has been reported to play a possible role in cancer-related EMT." (PMID 29568351, 2018). "In this study, we sought to confirm if ANXA2 is overexpressed in CRC human samples by analysing its expression in different stages of the disease, evaluate its prognostic value potential and explore the pathways through which ANXA2 overexpression leads to cancer progression." (PMID 30050103, 2018). "This review summarizes the mechanisms by which ANXA2 promotes cancer progression (e.g., proliferation, migration, the epithelial-mesenchymal transition, invasion, and cancer stem cell formation) and therapeutic resistance (e.g., radiotherapy, chemotherapy, and immunotherapy)." (PMID 29598816, 2018). "Alternatively, ANXA2 was previously identified as a potential therapeutic target in cancer." (PMID 29568351, 2018). "Due to broad approaches of biopsies, and serum and circulating CSC detection, ANXA2 might be a short-term clinical indicator for cancer patients." (PMID 29598816, 2018). "A lot of evidence suggests that Annexin A2 may be a promising therapeutic target for cancer treatment." (PMID 29508276, 2018). "ANXA2 was upregulated in all cancer stages (I–IV) when compared to normal controls." (PMID 30050103, 2018). "Likewise, previous studies indicate that Tyr23 phosphorylation of ANXA2 accelerates cancer cell migration, invasion and metastasis." (PMID 30081903, 2018). "Annexin-A2 has been shown to act in some cancers as a redox sink for peroxide molecules, thus allowing rapid detoxification of peroxide intermediates generated by the elevated metabolic rate of most cancer cells." (PMID 29443941, 2018). "They found that the Endo28 thioaptamer targets annexin A2, a protein upregulated in cancer." (PMID 28703779, 2017). "Various evidences showed that CD147 might enhance the migration and metastasis of cancer via Annexin A2/DOCK3-β-catenin- WAVE2, EGFR-src-Rac1-pSTAT3-DOCK8, integrin-FAK-PI3K/PIP3-Rac1-WAVE2 and FAK- PI3K/PIP3-Rac1-WAVE2 pathways." (PMID 29163835, 2017). "Fortunately, we found Annexin A2, a cancer-promoting protein, which could specifically bind to the (20S)G-Rh2-PEGA resin, but not the (20R)G-Rh2-PEGA resin." (PMID 28963461, 2017). "Extracellular ANXA2 has been demonstrated to be involved in many cancers." (PMID 28720835, 2017). "Moreover, recently studies showed that Annexin A2 appears to be involved in the drug resistance phenotype of cancer cells." (PMID 28886730, 2017). "Previous studies showed that P37 of Mycoplasma hyorhinis promoted migration of cancer cells by interacting with N-terminal of Annexin A2 (ANXA2) which is an Annexin family protein existing in numerous kinds of cells and associates with exocytosis, endocytosis and cell-cell adhesion." (PMID 28976984, 2017).